APCS (amyloid P component, serum)
Description:
Can interact with DNA and histones and may scavenge nuclear material released from damaged circulating cells. May also function as a calcium-dependent lectin.
Synonyms: SAP; PTX2; MGC88159; HEL-S-92n
Tractability: Small molecule: a drug acting on it is in phase 2 or 3 trials; a structure with a bound ligand is known; it has a high-quality binding pocket. Antibody: a drug acting on it is in phase 2 or 3 trials; its Gene Ontology location is reachable by antibodies, with high confidence; UniProt places it where antibodies can reach, with medium confidence; UniProt predicts a signal peptide or a membrane-spanning region. PROTAC: its protein half-life has been measured.
Target class: Secreted protein
Gene: Protein-coding gene on chromosome 1 (159,587,826 to 159,588,865, forward strand). Ensembl gene ENSG00000132703.
Subcellular location: Secreted
Pathways (Reactome):
Metabolism of proteins: Amyloid fiber formation
Gene Ontology:
Molecular function: calcium ion binding; complement component C1q complex binding; identical protein binding; protein binding; virion binding
Biological process: host-mediated suppression of symbiont invasion; innate immune response; negative regulation by host of viral glycoprotein metabolic process; negative regulation of glycoprotein metabolic process; negative regulation of monocyte differentiation; negative regulation of viral process; acute-phase response; chaperone-mediated protein complex assembly; negative regulation of acute inflammatory response; negative regulation of wound healing; protein folding
Cellular component: blood microparticle; extracellular exosome; extracellular region; nucleus
Genetic constraint (gnomAD): Loss-of-function variants: 4 observed, 4.06 expected, observed/expected ratio (o/e) 0.98, 90% interval 0.47 to 1.83. That is too few expected variants to judge how well the gene tolerates losing a copy. Missense variants: 302 observed, 271.02 expected, observed/expected ratio (o/e) 1.11, 90% interval 1.01 to 1.23. Synonymous variants: 109 observed, 108.72 expected, observed/expected ratio (o/e) 1, 90% interval 0.86 to 1.18.
Homologues: Orthologues: chimpanzee APCS (98% identical), macaque APCS (91% identical), pig APCS (77% identical), rabbit APCS (73% identical), guinea pig APCS (71% identical), rat Apcs (71% identical), mouse Apcs (69% identical), tropical clawed frog crp.2 (39% identical), tropical clawed frog apcs (38% identical), tropical clawed frog apcs.2 (38% identical), tropical clawed frog XB5856184 (37% identical), tropical clawed frog crp (32% identical), and 2 more. Paralogues in human: CRP (51% identical), NPTX2 (27% identical), PTX4 (26% identical), PTX3 (25% identical), NPTX1 (24% identical).
Diseases named in the same sentence as APCS in open-access papers:
APCS is named in the same sentence as 59 diseases in open-access papers, as found by Europe PMC text mining. Sharing a sentence is not in itself a finding about the gene and the disease. The quoted sentences say what the papers report.
amyloidosis (10 papers, 2013 to 2024). A disorder characterized by the localized or diffuse accumulation of amyloid protein in various anatomic sites. "APCS has been shown to stabilize amyloid plaques, prevent proteolysis, and promotes deposition of amyloid in vitro." (PMID 37414805, 2023). "APCS, also known as pentraxin-2, is involved in amyloidosis but it is also present in human atherosclerotic lesions." (PMID 31856737, 2019). "Furthermore, the disease-gene associations related to amyloidosis (Apolipoprotein E [APOE], C3, FGA, Transthyretin [TTR], and Serum amyloid P-component [APCS or SAMP]) showed significant enrichment (FDR = 2.66E-5)." (PMID 37875373, 2023).
Alzheimer disease (3 papers, 2023 to 2024). A progressive, neurodegenerative disease characterized by loss of function and death of nerve cells in several areas of the brain leading to loss of cognitive function such as memory and language. "APCS is also associated with a decrease in established Alzheimer’s disease, but its levels in those at risk and in pre-Alzheimer’s disease are not known." (PMID 38256230, 2024). "Amyloid P component (APCS) is found in plaques and the neurofibrillary tangles characteristic of Alzheimer’s disease, and its role may be involved in the decreased proteolysis of Aβ deposits, leading to further plaque formation therefore, increased serum levels may be detrimental." (PMID 38397086, 2024).
COVID-19 (3 papers, 2021 to 2022). A disease caused by infection with severe acute respiratory syndrome coronavirus 2. "Moreover, most acute phase proteins, such as SAA1, SAA2, SAA4, CRP, SERPINA3, and SAP/APCS, which were increased in severe COVID-19 patients were not changed in our CoronaVac immunized samples." (PMID 35686122, 2022).
Obesity (3 papers, 2023 to 2025). Accumulation of substantial excess body fat. "According to our results, APCS abundance have been found upregulated in plasma and EVs of individuals with obesity compared to lean controls, suggesting that this protein abundance may be the result of adaptation of the organism to the low-grade chronic inflammatory that underlies severe obesity." (PMID 38703299, 2024). "Other studies have linked obesity and weight change with CRP, APCS, ADIPOQ, C3 and other complement proteins, ORM1, and ORM222,34,36–38." (PMID 37794065, 2023). "BMI-predictive proteins included established obesity markers and obesity-related proteins, including adiponectin, CRP, IGFBP1, IGFBP2, PRG4, SHBG, apolipoproteins (APOA4, APOF) and inflammatory response proteins (A2M, APCS, LBP, HSPG2, HP, AOC3, ITGB1, VNN1)." (PMID 39972214, 2025). "However, the role of APCS in human obesity has not been clearly elucidated." (PMID 38703299, 2024).
Sepsis (3 papers, 2021 to 2022). Sepsis is defined as life-threatening organ dysfunction caused by a dysregulated host response to infection. "By bioinformatics analysis, we found evidence of APCS gene expression in human myelomonocytic progenitors, myeloid cells in acute coronary syndromes and in sepsis and myeloid murine cells." (PMID 34145258, 2021).
Stroke (3 papers, 2018 to 2024). Sudden impairment of blood flow to a part of the brain due to occlusion or rupture of an artery to the brain. "Based on our data, we suggest that CPN2, FXII, PLG, MASP1, APCS, PON1, and CA1 for IS and FBLN1 and GRN for ICH should be further scientifically pursued as potential stroke blood biomarkers." (PMID 34975707, 2021). "These drugs have also been shown to be protective in animal stroke models: wild-type activated protein C (WT-APC) is cytoprotective but also an anticoagulant; the engineered mutant APCs known as 5A and 3K3A-APC retain the APC cytoprotection but without the same anticoagulant potency." (PMID 38548341, 2024).
lupus nephritis (2 papers, 2008 to 2025). Glomerulonephritis in the context of systemic lupus erythematosus. "On the contrary, SAMP/APCS belonging to the pentatraxin family is able to regulate many aspects of the innate immune system and has been recognized as the most predictive marker of experimentally induced or lupus nephritis." (PMID 40427671, 2025).
aortic valve stenosis (1 paper, 2019). Aortic valve stenosis (AVS) is a condition characterized by narrowing of the heart's aortic valve opening. "We detected an upregulation of complement 9 (C9), serum amyloid P-component (APCS) and transgelin as well as downregulation of heat shock protein (HSP90), protein disulfide isomerase A3 (PDIA3), annexin A2 (ANXA2) and galectin-1 in patients with aortic valve stenosis." (PMID 31856737, 2019).
asthenozoospermia (1 paper, 2023). "In detail, the combination of the three proteins APCS, APOE, and FLOT1 predicts male subfertility in general, the two combined proteins APOE and FN1 predicts asthenozoospermia, and the two combined proteins RUVBL1 and TFKC oligoasthenozoospermia." (PMID 37048090, 2023).
colorectal cancer (1 paper, 2012). A primary or metastatic malignant neoplasm that affects the colon or rectum. "Here, RNA interference has been used to down-regulate truncated APC in several colorectal cancer cell lines expressing truncated APCs of different lengths, thereby performing an analysis covering most of the mutation cluster region (MCR)." (PMID 22509309, 2012).
coronary artery disease (1 paper, 2024). "Using variants within the cis–gene region of APCS, MR analyses detected a causal association of SAP with coronary artery disease and AD, though only to a marginal degree." (PMID 39766777, 2024).
dementia (1 paper, 2024). Loss of intellectual abilities interfering with an individual's social and occupational functions. "Secondly, previous GWAS of AD and other types of dementia have not reported APCS as a potential gene for disease onset." (PMID 39013416, 2024).
diabetes (1 paper, 2021). "Regardless of diabetes and its remission, we found three proteins (KNG1, ITIH2, and APCS) whose abundance changed after 6 months of bariatric surgery when considering all patients as a whole." (PMID 34501327, 2021).
fungal infection (1 paper, 2021). "In view of the critical role of SAP during fungal infection in vivo, we next investigated the relationship between genetic variation in the human APCS gene and susceptibility to IPA in patients at-risk." (PMID 34145258, 2021). "We now demonstrate that SNPs in APCS also contribute to IPA via molecular mechanisms influencing opsonisation and activation of the complement cascade in response to fungal infection." (PMID 34145258, 2021).
gout (1 paper, 2020). A condition characterized by painful swelling of the joints, which is caused by deposition of urate crystals. "However, APCS showed quite consistent expression patterns for all SF samples in western blot data, even though MS-based proteomics revealed significantly higher fold-changes of APCS protein in the AS group than the other groups (AS/RA: 15.69, AS/gout: 4.81, AS/OA: 6.53)." (PMID 32518534, 2020).
hyperandrogenemia (1 paper, 2024). "When stratified according to demographic parameters, hyperandrogenemia showed increased APCS, ApoE and ApoA1, whereas PAPPA was decreased." (PMID 38256230, 2024). "There was a difference when stratifying according to hyperandrogenemia, with APCS, ApoE and ApoA1 higher in hyperandrogenemia (p < 0.01, p < 0.04 and p < 0.01, respectively), while PAPPA was decreased in hyperandrogenemia (p < 0.01)." (PMID 38256230, 2024).
injury (1 paper, 2023). Damage inflicted on the body as the direct or indirect result of an external force, with or without disruption of structural continuity. "Henceforth, our results suggest APCS as a potential candidate protein which further can be explored to study its potential role in anti-tubercular drug induced liver injury." (PMID 37349331, 2023).
nonsmall cell lung cancer (1 paper, 2022). "APCS is a gene that codes serum amyloid P-component, which is one of the main acute-phase reactants and has reported to a biomarker for survival in nonsmall cell lung cancer after thoracic radiotherapy." (PMID 37223105, 2022).
pancreatic cancer (1 paper, 2025). "APCS has been demonstrated in pancreatic cancer to promote fibrosis through the TGF-β signaling pathway, suggesting it may play a role in stromal remodeling in HCC." (PMID 40649911, 2025).
infection (5 papers, 2014 to 2024). The state of being infected such as from the introduction of a foreign agent such as serum, vaccine, antigenic substance or organism. "Based on its specific and significant decrease in hepatotoxicity group and being a critical protein in combating the infection, APCS protein was shortlisted for further validation by ELISA." (PMID 37349331, 2023). "Seven infection/inflammation-related proteins in our assay, S100A9, VIM, LGALS1, APCS, MMP9, LDHA, and CRP, were elevated in TB-PEs and the other-infectious-PEs." (PMID 35197508, 2022).
tumor (4 papers, 2017 to 2026). "In the BF-TK/GCV/BF-TK group, the top five hub proteins were AMBP, HRG, APCS, HPX, and GIG25; some proteins (HRG, HPX, and GIG25) are positively associated with tumor metastasis." (PMID 37511481, 2023).
bacterial infection (2 papers, 2021 to 2022). "Serum amyloid P component (SAP, also known as Pentraxin 2; APCS gene) is a component of the humoral arm of innate immunity involved in resistance to bacterial infection and regulation of tissue remodeling." (PMID 34145258, 2021).
APCS also shares sentences with these, for which no sentence is quoted: pulmonary fibrosis (7 papers); cancer (3); idiopathic pulmonary fibrosis (2); Insulin resistance (2); lupus (2); acute coronary syndrome (1); adenocarcinoma (1); alcohol (1); Arthritis (1); atherosclerosis (1); autism spectrum disorder (1); autoimmune disease (1); Autoimmunity (1); breast carcinoma (1); CADASIL (1); cardiomyopathy (1); cardiovascular disease (1); Cognitive impairment (1); colitis (1); endotoxemia (1); gastric cancer (1); glomerulonephritis (1); hepatoblastoma (1); Hypertension (1); idiopathic dilated cardiomyopathy (1); kidney damage (1); kidney disease (1); Leukoencephalopathy (1); lipidosis (1); liver cancer (1).
A further 7 diseases each share a sentence with APCS in 1 paper.